SLC7A11 (solute carrier family 7 member 11)
Diseases named in the same sentence as SLC7A11 in open-access papers (continued):
Sharing a sentence is not in itself a finding about the gene and the disease.
head and neck squamous cell carcinoma (18 papers, 2021 to 2026). A squamous cell carcinoma that arises from any of the following anatomic sites: lip and oral cavity, nasal cavity, paranasal sinuses, pharynx, larynx, and salivary glands. "In head and neck squamous cell carcinoma, the implementation of FINs targeting SLC7A11 presents a promising approach to alleviate cisplatin resistance." (PMID 40275333, 2025). "The glutaminolysis-related genes, including ASCT2 and GDH-encoding GLUD, are suggested as biomarkers of the efficacy of SLC7A11 (xCT)-targeted therapy for heterogeneous head and neck squamous cell carcinoma tumors." (PMID 33868388, 2021). "Additionally, paracrine CCL2 from F. nucleatum-reprogrammed adipocytes upregulates SLC1A5 and SLC7A11 in head and neck squamous cell carcinoma (HNSCC), leading to glutathione (GSH) accumulation and cisplatin resistance." (PMID 41276817, 2025). "However, the SLC7A11 protein showed low expression levels in HPV-positive head and neck squamous cell carcinoma (HNSCC) when compared to HPV-negative cases." (PMID 39769017, 2024). "SLC7A11 expression inversely correlates with CD8+T cell infiltration in various tumors, such as head and neck squamous cell carcinoma." (PMID 39820491, 2025). "In head and neck squamous cell carcinoma (HNSCC) cells, SLC7A11 expression contributes to resistance to oxidative stress, and high expression of SLC7A11 and SLC1A5 is correlated with the dedifferentiation status of cancer cells." (PMID 35011702, 2022). "Furthermore, SLC7A11, IFN2, and MYH9 were significantly upregulated in kidney clear cell carcinoma (KIRC) and head and neck squamous cell carcinoma (HNSC)." (PMID 38862242, 2024).
neuroblastoma (18 papers, 2011 to 2025). Neuroblastoma (NB) is the most common solid, extracranial childhood tumor. "We have previously reported that exposure of SH-SY5Y neuroblastoma cells to unconjugated bilirubin (UCB) resulted in a marked up-regulation of the mRNA encoding for the Na+ -independent cystine∶glutamate exchanger System Xc− (SLC7A11 and SLC3A2 genes)." (PMID 22216172, 2011). "In SH‐SY5Y neuroblastoma cells, isoflurane induced ferroptosis and affected the activity of SLC7A11 by enhancing Beclin1 phosphorylation and formation of Beclin1‐SLC7A11 complex." (PMID 38334231, 2024). "Both neuroblastoma cell lines and primary neuroblastomas had the lowest SLC7A11 expression compared to other tumor entities." (PMID 35484422, 2022). "In particular, cell lines of the pediatric entities neuroblastoma and acute lymphoblastic leukemia, as well as adult entities lymphoma and acute myeloid leukemia, expressed SLC7A11 at a low level." (PMID 34503286, 2021). "A similar SLC7A11 expression pattern was observed in the INFORM patient cohort, with ALL, rhabdomyosarcoma, NHL and neuroblastoma being those with the lowest SLC7A11 expressions." (PMID 34503286, 2021). "We validated a ROS mediated mode of action in neuroblastoma and demonstrated a predictive value of SLC7A11 expression for discriminating responsive from less responsive entities." (PMID 34503286, 2021). "Our work addresses these challenges through two key innovations: First, we demonstrate that exogenous cystine supplementation bypasses intrinsic SLC7A11 dependency, enabling robust disulfidptosis in SLC7A11 low/intermediate neuroblastomas under glucose-deprived conditions." (PMID 41281650, 2025). "Of note, our study shows that forced expression of SLC7A11 prevents cell death of LRP8‐deficient neuroblastoma, but it also demonstrates its negative impact on the survival of these cells." (PMID 37435859, 2023). "However, despite these observations, we noted that SLC7A11 overexpression resulted in a profound growth defect of neuroblastoma cells." (PMID 37435859, 2023). "In general, neuroblastoma cells have very low SLC7A11 expression compared to other cancer types, which may explain the remarkable sensitivity of neuroblastoma cells to ferroptosis stimuli." (PMID 35484422, 2022). "Entities with rather low SLC7A11 expression levels (CCLE data) are neuroblastoma, ALL or NHL." (PMID 34503286, 2021). "While SLC7A11 indicates responsiveness quite well for tumor entities, we noticed that the correlation between SLC7A11 expression and APR-246/PRIMA-1 sensitivity (IC50) was reduced in neuroblastoma cell lines (Pearson correlation coefficient of 0.145)." (PMID 34503286, 2021). "Presumably differentiated neuroblastoma cell lines are more sensitive to RSL3 treatment (i.e., GPX4 inhibition) rather than erastin (the system xc- inhibitor) because these cells already have higher basal levels of cysteine due to the upregulation of SLC7A11 during the differentiation process." (PMID 39329725, 2024). "Upregulated expression of antioxidant genes, viz., HMOX1, NFE2l2, SLC7A11, and NADPH oxidase, and downregulated expression of monooxygenase enzymes in our study could be a putative approach to deal with the oxidative stress in WS-treated human neuroblastoma SK-N-SH cells." (PMID 40636521, 2025). "Publicly available data (depmap portal) indicate that in neuroblastomas, LRP8 dependency is inversely correlated with SLC7A11 expression with LRP8 knockout sensitive cell lines exhibiting lower SLC7A11 expression levels, while this is not observed for GPX4." (PMID 37435859, 2023).
pancreatic ductal adenocarcinoma (18 papers, 2008 to 2026). An infiltrating adenocarcinoma that arises from the epithelial cells of the pancreas. "Although the germline deletion of solute carrier family 7 member 11 (Slc7a11) is well tolerated in unstressed mice, Slc7a11 deficiency induces tumor-selective ferroptosis and inhibits pancreatic ductal adenocarcinoma (PDAC) growth." (PMID 33294126, 2020). "Recently, a group reported that pancreatic ductal adenocarcinoma cells employ the autophagy machinery to control the activity and localization of SLC7A11 on the cell's plasma membrane." (PMID 39569390, 2025). "Similarly, administration of a nanoparticle-based siRNA targeting SLC7A11 effectively suppressed tumor growth, reduced metastasis occurrence, inhibited activation of cancer-associated fibroblasts, and mitigated fibrosis in orthotopic pancreatic ductal adenocarcinoma tumors." (PMID 39569390, 2025). "Deletion of the SLC7A11 gene in genetically engineered mice with pancreatic ductal adenocarcinoma induced tumor-selective ferroptosis and inhibited tumor growth." (PMID 35525914, 2022). "For example, SLC7A11, a core target-regulating ferroptosis, is overexpressed and is correlated with worse survival in non-small cell lung cancer (NSCLC) and pancreatic ductal adenocarcinoma (PDAC) patients, which is classified as a suppressor of ferroptosis." (PMID 37675227, 2023). "Additionally, miR-485-3p, upregulated via hypoxia-induced epigenetic regulation, enhances pancreatic ductal adenocarcinoma (PDAC) cell stemness and gemcitabine resistance through SLC7A11-mediated ferroptosis." (PMID 41601687, 2026). "In pancreatic ductal adenocarcinoma (PDAC) cells, cysteine uptake could compensate for the intracellular cysteine pool when SLC7A11 is knocked out." (PMID 39079386, 2024). "Additionally, SLC7A11 was also found to be essential for tumor growth by relieving oxidative stress in some oncogenic KRAS-mutant cancers, including pancreatic ductal adenocarcinoma, colorectal adenocarcinoma and LUAD." (PMID 34996469, 2022).
cardiomyopathy (17 papers, 2021 to 2025). A disease of the heart muscle or myocardium proper. "Mice with FT-H-deficient cardiomyocytes showed increased cardiomyopathy associated with a reduced level of Slc7a11 and glutathione, and increased lipid peroxidation." (PMID 35160288, 2022). "Ferritin plays a key role in inhibiting cardiac ferroptosis and succedent heart failure, while cardiac ferritin H loss promotes cardiomyopathy by increasing SLC7A11-mediated ferroptosis." (PMID 35805124, 2022). "Cardiac ferritin H deficiency reduces SLC7A11 expression and facilitates ferroptosis and cardiomyopathy." (PMID 35805124, 2022). "Loss of FTH promoted cardiomyopathy through SLC7A11-mediated ferroptosis." (PMID 36398315, 2022). "It was first revealed in vivo that membrane protein SLC7A11 can effectively reverse cardiomyopathy caused by ferritin deficiency by blocking ferroptosis in cardiomyocytes, which is expected to become a new target for the prevention and treatment of heart diseases." (PMID 34413966, 2021). "A study found that the mitochondrial outer membrane protein FUNDC2 promotes cell ferroptosis by regulating the stability of the SLC7A11 protein, thereby participating in the molecular mechanism of Doxorubicin-induced cardiomyopathy." (PMID 37152941, 2023). "Recently it was reported that loss of cardiac Ferritin H could facilitate cardiomyopathy via SLC7A11, a crucial protein in disulfidptosis, mediated ferroptosis, indicating the potential role of disulfidptosis in the development of cardiomyopathy." (PMID 39701955, 2024). "Here, we show that activation of the ISR induces Slc7a11 upregulation in BTHS, and demonstrate that the activity of the system xCT is increased in the Taz-KD mouse heart in vivo, revealing a role for this transporter in human cardiomyopathy." (PMID 37930434, 2023).
ischemia (17 papers, 2020 to 2026). A hypoperfusion of the BLOOD through an organ or tissue caused by a PATHOLOGIC CONSTRICTION or obstruction of its BLOOD VESSELS, or an absence of BLOOD CIRCULATION. "Other studies have shown that EA activates the Nrf2/SLC7A11/GPX4 antioxidant pathway, suppresses lipid peroxidation, preserves mitochondrial integrity, and attenuates ischemia mitochondrial integrity Nrf2/SLC7A11/GPX4 antioxidant pathway." (PMID 41561334, 2025). "Simultaneously, ATF3 enhances cellular antioxidant capacity by regulating the expression of SLC7A11, alleviating intestinal ischemia-reperfusion injury and inhibiting ferroptosis." (PMID 41550926, 2025). "Injection of the SLC7A11 inhibitor Erastin reduced the expression of SLC7A11 and GPx4, indicating that 14 days of aerobic exercise can activate the Nrf2/SLC7A11/GPx4 pathway, thereby reducing sensitivity to ferroptosis in the ischemia–reperfusion brain model." (PMID 39315073, 2024). "Similar to NF-κB, phosphorylated STAT3 not only inhibits ferroptosis in intestinal ischemia/reperfusion-induced acute lung injury by positively regulating SLC7A11, but also induces ferroptosis in hypertensive mice by inactivating the SLC7A11/GPX4 signaling." (PMID 37153794, 2023). "Study shows that Nrf2 inhibits ferroptosis and protects intestinal ischemia-reperfusion induced acute lung injury by regulating SLC7A11 and HO-1." (PMID 34666603, 2021). "Further studies are needed to determine whether and how ARIP1 influences ferroptosis by altering glutamate signaling through SLC7A11 after ischemia." (PMID 40965963, 2025). "However, a study has shown that continuous treadmill exercise for 14 days, at 30 min per day and 10 meters/min, increased the expression of Nrf2, SLC7A11, and GPx4 in an ischemia–reperfusion brain model." (PMID 39315073, 2024). "Many studies provide direct evidence supporting the hypothesis that inhibition of SLC7A11 induces ferroptosis and aggravates ischemia." (PMID 37267686, 2023). "In addition, SLC7A11 was identified through transcriptomic analysis as a key regulatory gene involved in ferroptosis of cerebral microvascular endothelial cells, with its expression markedly downregulated following ischemia." (PMID 41273058, 2025).
hepatoblastoma (16 papers, 2022 to 2025). Hepatoblastoma (HB) is a malignant hepatic tumor and is the most common pediatric liver cancer. "However, the role and underlying mechanisms of SLC7A11‐mediated ferroptosis in hepatoblastoma (HB) remain largely unknown." (PMID 35522946, 2022). "As an m6A “reader”, IGF2BP2 has been shown to enhance the stability of SLC7A11 mRNA through m6A modification, thereby conferring ferroptosis resistance to hepatoblastomas." (PMID 39731162, 2024). "A recent study found that the expression of SLC7A11 increased in hepatoblastoma due to the METTL3-IGF2BP axis modifying and recognizing the SLC7A11 mRNA to stabilize it." (PMID 38392340, 2024). "METTL3/IGF2BP1-mediated m6A modification stabilizes SLC7A11 mRNA and upregulates SLC7A11 expression by inhibiting the deadenylation process in hepatoblastoma cells." (PMID 38072908, 2023). "Another study in hepatoblastoma reported that m6A-dependent inhibition of SLC7A11 deadenylation promotes tumorigenesis." (PMID 38023731, 2023). "METTL3-mediated m6A modification of SLC7A11 promotes ferroptosis resistance in hepatoblastoma cells." (PMID 38072908, 2023). "In contrast, SLC7A11 acts as an oncogene that promotes hepatoblastoma proliferation and enhances ferroptosis resistance in tumor cells." (PMID 36531055, 2022). "Not coincidentally, in the modification of SLC7A11 by METTL3, IGF2BP1 promoted the stability of SLC7A11 mRNA and upregulated its expression by inhibiting the process of demethylation thereby suppressing the sensitivity of hepatoblastoma to ferroptosis before leading to disease progression." (PMID 38550378, 2024). "The study showed that in hepatoblastoma, IGF2BP1 similarly acts as readers to recognize and bind m6A modifications in SLC7A11 mRNA, stabilize it and upregulate its expression in an m6A-dependent manner." (PMID 36531055, 2022). "Similarly, in hepatoblastoma, METTL3-mediated m6A modification increases the stability and expression of SLC7A11 mRNA, conferring resistance to ferroptosis and accelerating tumor growth." (PMID 40271153, 2025).
renal cell carcinoma (16 papers, 2019 to 2025). "It has been reported that SLC7A11 is upregulated in renal cell carcinoma, and its increased expression is associated with the inferior survival of affected patients; SLC7A11 silencing is associated with decreased migration, invasion, and proliferation of malignant cells." (PMID 38778030, 2024). "Mutations in BAP1 can cause various types of cancer, such as renal cell carcinoma and mesothelioma, and when BAP1 is mutated, the inhibition of SLC7A11 and the promotion of ferroptosis are lost." (PMID 36874967, 2023). "PDIA4 inhibits ferroptosis in renal cell carcinoma through the PERK/ATF4/SLC7A11 signaling pathway." (PMID 39544949, 2024). "ZONs inhibited the expression of GPX4 and SLC7A11 and elevated the levels of Fe2+ and ROS in renal cell carcinoma (RCC) cells, which promoted the occurrence of ferroptosis in tumorigenic mouse models." (PMID 39276361, 2024). "Overexpression of MSH3, particularly under conditions of glucose starvation and concurrent SLC7A11 overexpression, has been demonstrated to promote disulfidptosis in renal cell carcinoma (RCC) cells." (PMID 38685115, 2024). "Based on the positive expression of SLC7A11 and GPX4 in RCC tissues, we preliminarily concluded that ferroptosis may play a role in the occurrence and progression of renal cell carcinoma." (PMID 37807410, 2023). "However, whether SLC7A11 and GPX4 serve as an oncogene in renal cell carcinoma (RCC) remains unclear." (PMID 37807410, 2023).
breast tumor (15 papers, 2013 to 2025). "Using the TIMER dataset, SLC7A11 gene expression was positively associated, albeit weakly, in breast tumors with neutrophil (p = 2.0×10−24) and macrophage (p = 4.5×10−6) infiltration." (PMID 38073087, 2024). "Ferroptosis inducer targeting SLC7A11 can inhibit the growth of endocrine resistant ER+ breast tumors." (PMID 39833180, 2025). "In human breast tumor tissues, SLC7A11 levels were negatively or positively correlated with KCTD10 or USP18, respectively." (PMID 38959043, 2024). "The analysis again showed that primary breast tumors exhibited significantly higher SLC7A11 expression than did breast CTCs." (PMID 37339981, 2023). "Studies have shown that SLC7A11 plays a crucial role in the biology of breast tumor stem cells, leading to the design of various anti-SLC7A11 vaccine formulations, including DNA plasmid vaccines, virus-like particles (VLP), and bovine herpesvirus type 4 (BoHV-4) vaccines." (PMID 39973065, 2025). "To test this hypothesis, we examined SLC7A11 expression levels from an RNA-Seq dataset with 16 CTCs and 12 available primary breast tumor samples from matched patients." (PMID 37339981, 2023). "Because the sample size in this study was limited, we further compared SLC7A11 expression between primary breast tumor samples from The Cancer Genome Atlas dataset and breast CTCs from other studies (with the caveat that these datasets were not generated from matched patients)." (PMID 37339981, 2023). "Given breast tumor growth was significantly suppressed in an in vivo xenograft model following neddylation blockage and SLC7A11 inhibition, it promoted us to determine whether targeting KCTD10 or USP18 in combination with SLC7A11 inhibition could similarly affect tumor growth in this model." (PMID 38959043, 2024). "Finally, SLC7A11, which is functional subunit of the cystine/ glutamate transporter, plays an important role in breast tumor metastasis and maybe a potential target for cancer therapy." (PMID 23497265, 2013). "Apart from SLC7A8, all the following amino acid transporters, SLC7A5, SLC3A2, SLC7A11 and SLC38A2, were significantly expressed in breast tumours with high SLC1A5 expression (P < 0.01)." (PMID 39843491, 2025). "Our study revealed that SLC7A11 and SLC3A2 were found to be upregulated in endocrine resistant breast tumors and cancer cells." (PMID 39833180, 2025). "Compared with normal breast tissue, the expression of xCT components SLC7A11 and SLC3A2 is increased in a subset of patient breast tumor tissues, and their co-expression is closely related to the expression of GPX4." (PMID 35057861, 2022). "We observe that expression of the xCT components SLC7A11 and SLC3A2 are elevated in a subset of patient breast tumor tissues compared to normal breast tissue, and that their coordinated expression tightly correlates with GPX4 expression." (PMID 33672555, 2021). "Furthermore, upregulation of SLC7A11 and SLC3A2 proteins was observed in endocrine-resistant breast tumors compared with primary ER+ breast tumors." (PMID 39833180, 2025). "SLC7A11 protein expression was mainly observed in the cytoplasm of the invasive breast tumor cells, with intensity levels varying from absent to high." (PMID 38073087, 2024). "When directly examining protein levels from patient-derived breast tumor samples and normal breast tissues, we found that the expression levels of the xCT subunits, SLC7A11 and SLC3A2, were significantly upregulated in breast tumor tissues compared with normal tissues." (PMID 33672555, 2021). "In breast tumor samples specifically, IHC showed that absence of CD44 correlated with low signal from 18F-FSPG-PET, even if the SLC7A11 subunit was present, indicating possible importance of CD44 co-expression for system xC- function." (PMID 35294486, 2022).